VEGFA (vascular endothelial growth factor A)
Diseases named in the same sentence as VEGFA in open-access papers (continued):
Sharing a sentence is not in itself a finding about the gene and the disease.
colon carcinoma (continued). "The results of this study indicated the potential role of PVT1/VEGFA-enriched serum exosomes in promoting distant metastasis in colon cancer." (PMID 34336125, 2021). "M-exo were enriched with PVT1 and VEGFA, and both migratory and invasive abilities of colon cancer cell lines increased when they were cocultured with M-exo." (PMID 34336125, 2021). "VEGFA secreted by colon cancer cells stimulated CXCL1 production by TAMs, which recruited CXCR2+ MDSCs to promote liver metastasis." (PMID 34527668, 2021). "In this study, we examined OCR’s effects on cell viability, proliferation and vascular endothelial growth factor-a (VEGFa) expression in cultured cell lines human colon cancer cells (HCT116) and human umbilical vein endothelial cells (HUVEC)) in vitro." (PMID 34765545, 2021). "The results showed that the high expression of CCND1 and VEGFA was significantly correlated with poor prognosis of colon cancer (p < 0.05)." (PMID 34922547, 2021). "In human colon carcinoma, miR-299-3p suppresses the tumor process in the way of immediately targeting VEGFA." (PMID 32513149, 2020). "LINC01123 exerted as a miR-34c-5p sponge in colon cancer to promote VEGFA-triggered colon cancer malignancy and chemoresistance." (PMID 32700743, 2020). "In conclusion, LINC01123/miR-34c-5p/VEGFA axis promotes colon cancer malignancy and cells chemoresistance." (PMID 32700743, 2020). "Western blots were used to survey the inhibitory ability of Lactobacillus CFS on the protein levels of MMP2, MMP9, and VEGFA in colon cancer cells." (PMID 33228670, 2020). "It has been reported that IGF1 can stimulate VEGFA mRNA expression by stabilizing HIF1A protein in human colon cancer cell line HCT116." (PMID 32041892, 2020). "In the end, rescue assays illustrated that LINC01123 regulates the development and chemoresistance of colon cancer cells dependent on miR-34c-5p and VEGFA." (PMID 32700743, 2020). "We further verified the effective compounds, by analysing the key genes MMP2, MMP9, and VEGFA in the VEGF-MMPs signalling pathway of colon cancer cells using real-time (RT)-PCR." (PMID 33228670, 2020). "For instance, Geng and co-workers evidenced that TGFβ1 decreased VEGFA expression via Smad3P activation in colon cancer cells." (PMID 31632347, 2019). "MVD was correlated to expression of VEGFA in stage II colon cancer (correlation coefficient − 0.331, p = 0.020)." (PMID 31420015, 2019). "Aberrant splicing of VEGFA, leading to an alteration in the pro/anti-angiogenic ratio was described in human colon cancer." (PMID 30736462, 2019). "Coincidentally, the combination of ANGPT2 and VEGFA inhibition and PD-1 blockade was shown to improve tumor control, supporting the rationale for co-targeting angiogenesis and immune checkpoints for colon cancer therapy." (PMID 30042763, 2018). "In view of these results, we suggest the combination of anti-PD-1 or anti-PD-L1 antibodies and VEGFA inhibition should be of particular interest for the treatment of right-side colon cancer." (PMID 30042763, 2018). "A moderate positive correlation of RBP4 was observed with VEGFA in the primary colon cancer (r = 0.605) and with VEGFA (r = 0.631) and MYC (r = 0.499) in liver metastases." (PMID 28689994, 2017). "Using an in vitro model based on a colon carcinoma cell line, in which we forced MR expression, we also provide the evidence that activated MR can attenuate the expression of VEGFA and its receptor 2/KDR." (PMID 23555666, 2013). "Taken together with the observation that PKA activation is Smad3-dependent, these results indicate that TGF-beta/Smad3/PKA signaling regulates downregulation of VEGFA expression in colon cancer cells." (PMID 23536895, 2013). "In summary, we have identified a novel mechanism by which TGF-beta suppresses VEGFA expression, angiogenesis and metastasis in a subset of colon cancer cells." (PMID 23536895, 2013).
colon carcinoma (continued). "IHC studies performed on human colon adenocarcinoma specimens showed that TGF-beta signaling is inversely correlated with VEGFA expression, indicating that TGF-beta-mediated suppression of VEGFA expression exists in colon cancer patients." (PMID 23536895, 2013). "In colon cancer cell lines, Wnt signaling can increase transcription of VEGFA, and elevated levels of VEGFA have been detected in intestinal polyps of APCmin/+ mice and in human colon cancers relative to matched normal colon tissues." (PMID 20087418, 2010). "Moreover, PKN2 inhibited the expression and secretion of VEGFA and bFGF by colon cancer cells by inhibiting the binding of HIF‐1α to the VEGFA and bFGF promoter regions." (PMID 40515512, 2025). "In the present study, we found a strong negative correlation between WNT5A and VEGFA expression in a colon cancer cohort (GSE44076) and that Foxy5 induced a limited (approximately 40%) downregulation of VEGFA expression in colon cancer cells and in colon cancer tissue." (PMID 37998393, 2023). "The results revealed a clear reduction in VEGFA mRNA expression in the colon cancer tissue from Foxy5-treated mice when compared to that from vehicle-treated mice, but the reduction was not statistically significant due to large standard deviations and a limited number of mice." (PMID 37998393, 2023). "We analyzed the relationship between mRNA expression and OS in this network, and we found that high expression of CCND1 and VEGFA is an indicator of poor prognosis for colon cancer and that the expression of CCND1 and VEGFA is associated with macrophage infiltration." (PMID 34922547, 2021). "MicroRNA-299-3p inhibits the proliferation and invasion of colon cancer cells by targeting VEGFA." (PMID 33535182, 2021). "First, we demonstrated that exosomes obtained from patients with metastasis significantly enhanced the migratory and invasive abilities of human colon cancer cell lines HCT116 and LoVo in association with the increased expression of vascular endothelial growth factor A (VEGFA), vimentin, and MMP2." (PMID 34336125, 2021). "VEGFA was reported to promote angiogenesis in cancers, including colon cancer." (PMID 32700743, 2020). "Finally, LINC01123 was proofed to regulate colon cancer progression and cells chemoresistance via VEGFA." (PMID 32700743, 2020). "Inhibition of SUMO1P3 repressed proliferation, migration, invasion and pro-angiogenesis of colon cancer cells in vitro, and reduced growth, liver metastasis and vascularization of colon cancer in vivo by decreasing cyclin D1, vimentin and VEGFA but increasing E-cadherin expression." (PMID 32185172, 2020). "Conversely, miR-192 suppresses the ZEB2 and VEGFA expressions in colon cancer cells." (PMID 31590680, 2019). "The genes with switches identified by our data (e.g., VEGFA) are involved in a variety of cancers including skin, pancreatic and colon cancer, as well as lung disease according to our enrichment analysis, which is in agreement with previous studies for the mentioned gene." (PMID 30857150, 2019). "VEGFA-189 stimulates the growth of colon tumors in vivo, but to a lesser extent than VEGFA-165." (PMID 29888133, 2018). "The miRNA activity may also be only efficient in the cancer context since the microenvironment has been reported as an important factor for miRNA inhibition of VEGFA in pancreatic or human colon cancers." (PMID 29137669, 2017). "Readthrough has been demonstrated in human vascular endothelial growth factor A (VEGF-A), producing an isoform that reverses the angiogenic properties of VEGF-A, is regulated by a ribosomal binding protein, and is suppressed in colon cancer cells, having direct relevance to cancer treatment." (PMID 27604222, 2016). "Since TGF-beta acts as a metastasis suppressor in colon cancer cells, we examined whether suppression of VEGFA expression by TGF-beta contributes to metastasis suppression function of TGF-beta." (PMID 23536895, 2013).
colon carcinoma (continued). "Our studies suggest that activation or restoration of TGF-beta signaling in a sub-population of colon cancer patients may improve their response to anti-VEGFA therapies." (PMID 23536895, 2013). "Furthermore, an inverse relationship between TGF-beta signaling and VEGFA expression is also observed in human colon cancer specimens, indicating the relevance of our studies to human cancer." (PMID 23536895, 2013). "However, other NPY receptors have been implicated in promoting tumorigenicity in other cancers; for example, NPY2R is up-regulated in vascular endothelial growth factor A–depleted orthotopic models of colon cancer, and NPY2R antagonists inhibited angiogenesis and tumor growth in these models." (PMID 40073121, 2025). "Therefore, we examined the prognosis of colon cancer patients who express high levels of VEGFA." (PMID 37998393, 2023). "Finally, IHC studies of sections of human colonic adenocarcinomas reveal that TGF-beta signaling is inversely correlated with VEGFA expression, indicating that the link between loss of TGF-beta activity and increased VEGFA expression also exists in colon cancer patients." (PMID 23536895, 2013). "Based on these literature data and on our results from the analysis of VEGFA mRNA expression in MR-transfected colon cancer cells grown under normoxic conditions upon activation by the relative agonists, we suggest that MR may inhibit deregulated angiogenesis in CRC." (PMID 23555666, 2013). "Cellular experiments confirmed aspirin downregulated metastasis‐related genes (E2F1, CCNE1, VEGFA, MMP3) in colon cancer." (PMID 41425852, 2025). "Our findings demonstrated a significant reduction in VEGFA and bFGF expression in PKN2‐overexpressing colon cancer cells compared to control cells, while other proangiogenic factors remained unchanged." (PMID 40515512, 2025). "To validate our data analysis results, we extracted total RNA from patient colon cancer tissue and corresponding normal colon epithelial tissue and measured the mRNA expression levels of TIMP1, VEGFA, MYC, MSLN, EPHA2, ABHD2, and CD24." (PMID 38773226, 2024). "Anti-vascular endothelial growth factor-A (VEGFA) antibody was reported to greatly limit tumor growth and reduce the levels of TOX and NFAT in mouse colon cancer models." (PMID 37398660, 2023). "For example, miR-19a inhibits colon cancer angiogenesis by targeting KRAS and VEGFA, and miR-181d reduces cell proliferation, migration, and invasion by triggering PEAK1, a downstream regulator of the EGFR/KRAS pathway." (PMID 36960218, 2023). "In vitro, we found that OCR inhibited Human colon cancer cells (HCT116) and HUVEC cell proliferation and inhibited vascular endothelial growth factor-a (VEGFa) mRNA and protein expression in HUVECs in a co-culture system." (PMID 34765545, 2021). "The aim of this study was to examine the relation of MVD to disease-recurrence, in both stage II and stage III colon cancer patients, while taking into account the amount of tumour stroma (TSP) and expression of HIF1A and VEGFA." (PMID 31420015, 2019). "This study aimed to evaluate the prognostic value of MVD in stage II and III colon cancer and its relation to tumour-stroma-percentage (TSP) and expression of HIF1A and VEGFA." (PMID 31420015, 2019). "In this study, we report that, in colon cancer cells, TGF-beta inhibits VEGFA expression at the post-transcriptional level, probably by decreasing VEGFA protein stability through ubiquitination and degradation." (PMID 23536895, 2013). "Sections prepared from 10 normal colon and 24 individual colon cancer patients were examined for active TGF-beta signaling and VEGFA expression." (PMID 23536895, 2013). "In colon cancer, members of the miR-17–92 cluster activate Wnt/β-catenin signaling and epithelial-mesenchymal transition, while suppressing TGF-β signaling via direct targeting of TGFBR2, VEGFA and HIF1A." (PMID 41473312, 2025).
colon carcinoma (continued). "Additionally, we investigated the levels of secreted VEGFA and bFGF in the culture supernatant of PKN2‐overexpressing, PKN2‐knockdown, and control colon cancer cells." (PMID 40515512, 2025). "Moreover, it has been proved that lactoferrin could reduce the growth of blood vessels in colon cancer cells and the mechanism was validated to be associated with the inhibition of angiogenesis related pathways, including VEGFR2, vascular endothelial growth factor A (VEGFA), PI3K, Akt, and Erk1/2." (PMID 38298540, 2023). "Moreover, cell line experiments exhibited increased PVT1 levels in HT29 colon spheres compared with their parental counterparts along with increased VEGFA and EGFR levels, the two major metastatic or oncogenic markers in colon cancer." (PMID 34336125, 2021). "In the right-side tumor, when patients were grouped based on VEGFA expression, we found a twofold decrease in CD8A expression, and observed a negative correlation (r = −0.3903, *p = 0.0441) between VEGFA and CD8A expression in right-side colon cancer." (PMID 30042763, 2018). "For instance, in a very large‐scale study of breast, lung, and colon cancer, it has been very recently shown that plasmatic levels of VEGFA did not correlate with intratumoral levels of VEGFA." (PMID 25602014, 2015). "Importantly, aspirin also inhibited the expression of four highly expressed metastatic genes in colon cancer, including E2F1, CCNE1, VEGFA, and MMP3, which may explain its anti‐tumor and anti‐metastasis effect." (PMID 41425852, 2025). "In addition, we confirmed at the cellular level that aspirin has the ability to inhibit the metastasis of colon cancer cells and demonstrated that aspirin can suppress the expression of metastasis‐related genes (E2F1, VEGFA, MMP3, and CCNE1) in colon cancer cells." (PMID 41425852, 2025). "For example, in orthotopic tumor models of breast and colon cancer cells, GPR4 is activated after pH reduction and promotes tumor growth and pathological angiogenesis through p38-mediated secretion of interleukin-6 (IL-6), IL-8, and vascular endothelial growth factor-A (VEGF-A)." (PMID 38505262, 2024). "In addition, 2′-FL could also be specifically sensitive to a certain type of colon cancer cell, such as HCT116, and its mechanism was proved to be related to the VEGFA/VEGFR2/PI3K/Akt pathway, and it could also induce downstream apoptosis factors." (PMID 36364081, 2022). "VEGFA also facilitates the invasion of cancer cells via the VEGFA/VEGFAR pathway by activating p38 mitogen-activated protein kinase MAPK and phosphatidylkinase B (AKT) in order to induce MMP expression, which are widely used to indicate the metastatic capability of colon cancer cells." (PMID 33228670, 2020). "miR-192-5p decreased the liver metastasis of colon cancer in an orthotopic mouse model of colon cancer through targeting the expression of several oncogenic genes, including anti-apoptotic BCL2, Wnt/β-catenin activator called zinc finger E-box binding homeobox 2 (ZEB2) and pro-angiogenic VEGFA." (PMID 32610706, 2020). "Transcriptome analysis of 57 advanced colon cancer samples revealed that one of the non-T cell inflamed subtypes (group 4) had low expression of CD8a, IFNG and GZMB with high expression of SCD1 and CTNNB1(β-catenin) and its downstream molecules including VEGFA and TCF12." (PMID 35793868, 2022).
prostate carcinoma (525 papers, 2000 to 2026). A carcinoma that arises from epithelial cells of the prostate gland. "The VEGFA gene has been implicated in types of cancer, including prostate cancer, as a validation gene query based on a cBioprtal 4% alteration in 4946 sample repositories suggests." (PMID 37048688, 2023). "Some genetic variants in the VEGFA gene may influence the risk of high-grade late rectal toxicity after radiotherapy for prostate cancer." (PMID 32235817, 2020). "In contrast, TNS4 exhibits tumor-suppressor–like functions in breast and prostate cancers, where its downregulation promotes tumor growth and angiogenesis via the c-Cbl/β-catenin/VEGFA axis or disrupts normal growth-regulating pathways." (PMID 41439026, 2025). "VEGFA, or vascular endothelial growth factor A, is a crucial mediator of angiogenesis and is over-expressed in prostate cancer, promoting tumor growth and metastasis by enhancing vascularization." (PMID 39364872, 2025). "Prostate cancer tissue demonstrated significantly higher levels of VEGFA expression compared to healthy tissue." (PMID 38791417, 2024). "Studies have linked the onset and progression of prostate cancer to three genes related to hypoxia: P4HA1, ANGPLT4, and VEGFA." (PMID 38791417, 2024). "VEGFA is responsible for stimulating angiogenesis and is known to be overactive in various cancers, including prostate cancer." (PMID 38791417, 2024). "The mRNA level of hub gene VEGFA was found to be significantly higher in patients with prostate cancer than in normal prostate tissue." (PMID 37099169, 2023). "We found that ligustilide can inhibit the secretion of VEGFA from prostate cancer-related fibroblasts (CAFs), and this signaling pathway is related to Toll-like receptor 4 (TLR4)-ERK/JNK/p38." (PMID 35626012, 2022). "It was demonstrated that adiponectin overexpression in prostate cancer cells results in the depletion of vascular endothelial growth factor A (VEGFA) and vice versa via an AMPK/TSC2-mediated mechanism." (PMID 36292657, 2022). "Accordingly, it has been established that VEGFA overexpression can eliminate the anti-angiogenic effect induced by miR-130 b in prostate cancer." (PMID 35433661, 2022). "SRPK1 silencing in prostate cancer cells was found to result in preferential splicing of the anti-angiogenic VEGFA isoform." (PMID 35583632, 2022). "After topological enrichment, the most connected upregulated genes MYC, CDK1, CCNB1 etc. and the most connected downregulated genes EGFR, VEGFA, STAT3 etc. were categorized according to their highest degree count associated with prostate cancer." (PMID 35456461, 2022). "Another report showed that miR-30d promotes angiogenesis and tumor growth of prostate cancer cells via the MYPT1/c-JUN/VEGFA pathway." (PMID 33824274, 2021). "In PC-3 prostate cancer cells, we found a significant downregulation of VEGFA mRNA and protein secretion, indicating a lower metastatic potential of the cells when exposed to microgravity." (PMID 32070055, 2020). "In well differentiated tumor type the up regulation of VEGFA was identified as a key central node in young prostate cancer patients and down regulation of NPY in old men." (PMID 33575208, 2020). "Of note, we found a strong trend between GRK3 protein level and glomeruloid microvascular proliferation, a marker of VEGFA–driven angiogenesis, in prostate cancer patient samples." (PMID 32039001, 2019). "KDM1A regulates the expression of vascular endothelial growth factor A (VEGF-A), which is important in prostate cancer progression." (PMID 29921310, 2018). "KLK4 activated protease‐activated receptor‐1 in WPMY1 cells increasing expression of several factors (FGF1, TAGLN, LOX, IL8, VEGFA) involved in prostate cancer progression." (PMID 28510269, 2017). "Regarding the chronic inflammatory process, GSD and prostate cancer share several inflammatory genes, such as interleukin-8 and vascular endothelial growth factor A." (PMID 27147576, 2016).